HCG9 (HLA complex group 9)
Synonyms: PERB11; HCGIX; HCGIX4; HCGIX-4
Gene: Long non-coding RNA gene on chromosome 6 (29,975,112 to 29,978,586, forward strand). Ensembl gene ENSG00000204625.
Diseases named in the same sentence as HCG9 in open-access papers:
HCG9 is named in the same sentence as 17 diseases in open-access papers, as found by Europe PMC text mining. Sharing a sentence is not in itself a finding about the gene and the disease. The quoted sentences say what the papers report.
bipolar disorder (3 papers, 2014 to 2024). A disorder of the brain that causes unusual shifts in mood, energy, activity levels and the ability to carry out day-to-day tasks. "Several studies have found an association between HCG9 gene changes and bipolar disorder." (PMID 38792557, 2024). "HCG9 was identified in patients with schizophrenia or bipolar disorder in an MWAS of frontal cortex and in brain, blood and sperm in an MWAS for bipolar disorder." (PMID 25229548, 2014).
breast carcinoma (2 papers, 2021 to 2024). "Our study showed that low expression of HCG9 and high expression of PHTF2 resulted in the high survival rate of breast cancer patients." (PMID 38978021, 2024). "HCG9 has been briefly reported in breast cancer and gastric cancer but never in osteosarcoma." (PMID 34456631, 2021).
Hodgkins lymphoma (2 papers, 2012 to 2014). A heterogeneous group of malignant lymphoid neoplasms of B-cell origin characterized histologically by the presence of Hodgkin and Reed-Sternberg (HRS) cells in the vast majority of cases. "HLA-A and HCG9 were reportedly associated with the development of EBV-associated Hodgkin lymphoma and infectious mononucleosis (IM) after primary EBV infection." (PMID 22440091, 2012).
nasopharyngeal carcinoma (2 papers, 2021 to 2025). A carcinoma arising from the nasopharyngeal epithelium. "HCG9 is also known as the human leukocyte antigen complex group 9 gene, and studies have reported that HCG9 was related to lung squamous cell carcinoma and nasopharyngeal carcinoma." (PMID 34456631, 2021).
osteosarcoma (2 papers, 2021 to 2024). A usually aggressive malignant bone-forming mesenchymal neoplasm, predominantly affecting adolescents and young adults. "HCG9 gene expression increased in osteosarcoma tissues and cell lines, and high HCG9 expression was particularly associated with osteosarcoma metastasis." (PMID 34456631, 2021). "Further bioinformatic analysis showed that high HCG9 expression was associated with osteosarcoma progression." (PMID 34456631, 2021). "The Kaplan-Meier plot showed that the overall survival rate was significantly lower (P = 0.024) in the HCG9 high expression group compared with the low expression group, suggesting HCG9 was associated with the prognosis of osteosarcoma patients." (PMID 34456631, 2021). "Knockdown of HCG9 significantly suppressed osteosarcoma cell proliferation, migration, and invasion, demonstrating an oncogenic role of HCG9." (PMID 34456631, 2021). "Additional validation was conducted by comparing HCG9 expression in clinical osteosarcoma samples with paracarcinoma tissues, and abnormally elevated HCG9 expression was confirmed in tumor samples." (PMID 34456631, 2021). "The qRT-PCR result demonstrated that HCG9 gene expression was significantly upregulated in osteosarcoma tumor tissues as compared to paracarcinoma tissues." (PMID 34456631, 2021). "We discovered that lncRNA HCG9 promoted the proliferation of osteosarcoma cells via suppressing miR-34b-3p." (PMID 34456631, 2021). "We next investigated how HCG9 expression impacted the proliferation and apoptosis of osteosarcoma cells." (PMID 34456631, 2021). "Osteosarcoma tissues and cell lines expressed higher levels of HCG9 as compared to normal tissues and osteoblasts, and high expression of HCG9 was further proved to be related to metastasis and the grade of osteosarcoma in clinical cases." (PMID 34456631, 2021). "Overexpressing HCG9 promoted osteosarcoma cell proliferation, migration, and invasion in vitro, as well as aggravated tumor progression in vivo." (PMID 34456631, 2021). "In this study, we performed lncRNA microarray analysis and identified HCG9 as one of the differentially expressed lncRNAs in osteosarcoma tissues." (PMID 34456631, 2021). "The proliferation, migration, and invasion of osteosarcoma cells responded to the alteration of HCG9 gene expression." (PMID 34456631, 2021). "The impact of HCG9 knockdown and overexpression on osteosarcoma cells in vitro and tumor progression in vivo was evaluated." (PMID 34456631, 2021). "Cooverexpressing miR-34b-3p with HCG9 partially suppressed the HCG9-stimulated proliferation, migration, and invasion of osteosarcoma cells in vitro and delayed the tumor progression in vivo." (PMID 34456631, 2021). "By overexpressing miR-34b-3p, the in vitro hyperproliferation, migration, and invasion, as well as in vivo tumor growth stimulated by HCG9 overexpression, were mitigated, suggesting a potential protective role of miR-34b-3p in osteosarcoma progression." (PMID 34456631, 2021). "Using KEGG pathway analysis, we discovered that the high expression of HCG9 was correlated with the metastasis of osteosarcoma." (PMID 34456631, 2021). "Overexpressing HCG9 promoted RAD51 expression and suppressed H2A.X expression, indicating HCG9 induced mitosis and hyperproliferation of the osteosarcoma cells." (PMID 34456631, 2021). "We evaluated the role of HCG9 and miR-34b-3p in regulating osteosarcoma progression in vivo using a nude mouse model." (PMID 34456631, 2021). "In our current study, we developed a genome-wide approach to link lncRNA HCG9 to clinicopathological features of osteosarcoma, especially metastasis." (PMID 34456631, 2021). "HCG9 can facilitate the proliferation of osteosarcoma cells by inhibiting miR-34b-3p." (PMID 38339157, 2024). "Knockdown of HCG9 inhibited the proliferation, migration, and invasion of osteosarcoma cells." (PMID 34456631, 2021).
osteosarcoma (continued). "In summary, our data demonstrated that HCG9 negatively regulated miR-34b-3p, and abnormally low expressions of miR-34b-3p in osteosarcoma tumor tissues supported our hypothesis." (PMID 34456631, 2021). "Cooverexpression of miR-34b-3p and HCG9 was able to attenuate the osteosarcoma progression." (PMID 34456631, 2021). "Therefore, we further validated HCG9 gene expression in osteosarcoma and paracarcinoma tissues collected from patients." (PMID 34456631, 2021). "Six genes presented statistically significant expressions (P < 0.05) in osteosarcoma tissues versus paracarcinoma tissues and were screened, which were MALAT1, HCG9, FAM99A, FAM87B, DLEU2, and C8orf49." (PMID 34456631, 2021). "Herein, we screened 6 osteosarcoma-related genes by lncRNA microarray, MALAT1, HCG9, FAM99A, FAM87B, DLEU2, and C8orf49." (PMID 34456631, 2021). "HCG9 gene expression was also assessed in human fetal osteoblast cell line hFOB1.19 and osteosarcoma cell lines U2OS, MG-63, and MNNG/HOS, and the expression was enhanced in all three osteosarcoma cell lines as compared to hFOB1.19 cells." (PMID 34456631, 2021).
asthma (1 paper, 2024). "Cluster 5, which includes genes at 6p22.1 (HLA-A, HCG4P5, HLA-T, MOG, TRIM26, HCG9, IFITM4P), demonstrated further connections between JIA and a subset of autoimmune/inflammatory traits (i.e., type 1 diabetes, asthma, eczema, and severe COVID-19 or rheumatoid arthritis)." (PMID 39175752, 2024).
cancer (1 paper, 2021). A tumor composed of atypical neoplastic, often pleomorphic cells that invade other tissues. "High HCG9 expression was associated with cancer metastasis and grade but not the other pathological features such as age and gender." (PMID 34456631, 2021). "By analyzing CCLE, we found that HCG9 was associated with various cancer progressions." (PMID 34456631, 2021). "We discovered that high HCG9 was correlated with metastasis and severe cancer grades." (PMID 34456631, 2021). "We analyzed HCG9 gene expression in the Cancer Cell Line Encyclopedia (CCLE) database and found that HCG9 gene expression was elevated in various cancer cell lines." (PMID 34456631, 2021).
infection (1 paper, 2012). The state of being infected such as from the introduction of a foreign agent such as serum, vaccine, antigenic substance or organism. "Further, MS analysis showed that infection of chimeric mice with HCG9 (genotype 1a) was associated with increased SM levels in hepatocytes." (PMID 22916015, 2012).
tumor (1 paper, 2021). "The in vivo results confirmed that HCG9 aggravated tumor progression and miR-34b-3p reversed such effect." (PMID 34456631, 2021). "The immunohistochemistry staining result showed excessive Ki67-positive cells in the HCG9 overexpressing group, and the HCG9/miR-34b-3p cooverexpressing group partially reduced the Ki67-positive cell number, indicating miR-34b-3p mitigated the tumor aggressiveness stimulated by HCG9." (PMID 34456631, 2021).
HCG9 also shares sentences with these, for which no sentence is quoted: infectious mononucleosis (2 papers); COVID-19 (1); eczema (1); gastric cancer (1); lung squamous cell carcinoma (1); rheumatoid arthritis (1); schizophrenia (1); type 1 diabetes (1).